SEMA5B (semaphorin 5B)
Description:
May act as a positive axonal guidance cue.
Synonyms: KIAA1445; SEMAG; SemG; FLJ10372
Tractability: Antibody: UniProt predicts a signal peptide or a membrane-spanning region; its Gene Ontology location is reachable by antibodies, with medium confidence. PROTAC: its protein half-life has been measured.
Gene: Protein-coding gene on chromosome 3 (122,908,792 to 123,028,605, reverse strand). Ensembl gene ENSG00000082684.
Subcellular location: Membrane
Subcellular location (Human Protein Atlas): Cytosol
Pathways (Reactome):
Disease: Defective B3GALTL causes PpS
Metabolism of proteins: O-glycosylation of TSR domain-containing proteins
Gene Ontology:
Molecular function: chemorepellent activity; semaphorin receptor binding
Biological process: axon extension; axon guidance; neural crest cell migration; positive regulation of cell migration; semaphorin-plexin signaling pathway; negative chemotaxis
Cellular component: cytosol; plasma membrane; membrane
Genetic constraint (gnomAD): Loss-of-function variants: 62 observed, 118.71 expected, observed/expected ratio (o/e) 0.52, 90% interval 0.43 to 0.64. The upper end of that interval is the gene's LOEUF score, 0.64, which puts it in group 2 of 6, group 1 being the genes least tolerant of losing a copy. Missense variants: 1,491 observed, 1,488.4 expected, observed/expected ratio (o/e) 1, 90% interval 0.96 to 1.04. Synonymous variants: 688 observed, 606.09 expected, observed/expected ratio (o/e) 1.14, 90% interval 1.07 to 1.21.
Homologues: Orthologues: chimpanzee SEMA5B (99% identical), macaque SEMA5B (90% identical), pig SEMA5B (90% identical), dog SEMA5B (90% identical), mouse Sema5b (89% identical), rat Sema5b (89% identical), rabbit SEMA5B (87% identical), guinea pig SEMA5B (83% identical), tropical clawed frog sema5b (64% identical), zebrafish sema5ba (63% identical), zebrafish sema5bb (60% identical). Paralogues in human: SEMA5A (54% identical), SEMA3B (20% identical), SEMA3A (19% identical), SEMA6D (19% identical), SEMA3F (19% identical), SEMA4C (19% identical), SEMA6B (19% identical), SEMA4B (19% identical), SEMA6C (19% identical), SEMA3D (18% identical), SEMA3C (18% identical), SEMA4A (18% identical), and 7 more.
Diseases named in the same sentence as SEMA5B in open-access papers:
SEMA5B is named in the same sentence as 23 diseases in open-access papers, as found by Europe PMC text mining. Sharing a sentence is not in itself a finding about the gene and the disease. The quoted sentences say what the papers report.
clear cell renal carcinoma (2 papers, 2020 to 2022). A malignant epithelial neoplasm of the kidney characterized by the presence of lipid-containing clear cells within a vascular network. "The expression level of SEMA5B was upregulated in clear cell renal cell carcinoma (ccRCC) tissues, and suppression of SEMA5B inhibited the proliferative capacity of cancer cells, indicating SEMA5B might play an oncogenic role in ccRCC." (PMID 33224866, 2020). "In this study, we observed prominent upregulated mRNA and protein expression of SEMA5B in KIRC and clear cell renal carcinoma cell lines." (PMID 35480320, 2022). "Although early study has reported SEMA5B upregulation in clear cell renal carcinoma (ccRCC) and suggested the role of SEMA5B in tumor growth, there is a lack of comprehensive studies on the clinical role of SEMA5B." (PMID 35480320, 2022).
gastric adenocarcinoma (2 papers, 2022). "A recent study has shown that the upregulated SEMA5B was closely related to the prognosis of gastric adenocarcinoma." (PMID 35480320, 2022). "The overexpression of SEMA5B has been linked to the development and proliferation of RCC cells and poor prognosis in gastric adenocarcinoma." (PMID 36354023, 2022).
acute kidney injury (1 paper, 2022). Sudden and sustained deterioration of the kidney function characterized by decreased glomerular filtration rate, increased serum creatinine or oliguria. "In cardiac surgery patients at high risk for postoperative acute kidney injury, increased HMGB1 and Sema5b levels after RIPC were associated with renal protection after surgery." (PMID 35727636, 2022).
Alzheimer disease (1 paper, 2022). A progressive, neurodegenerative disease characterized by loss of function and death of nerve cells in several areas of the brain leading to loss of cognitive function such as memory and language. "We hypothesize that SEMA5B expression and function may change as Alzheimer’s disease progresses, though further mechanistic study of SEMA5B in relevant brain tissues is truly needed to confirm its role and function in neurodegeneration." (PMID 35425899, 2022).
amyloidosis (1 paper, 2022). A disorder characterized by the localized or diffuse accumulation of amyloid protein in various anatomic sites. "Thus, it may be that higher expression of SEMA5B is associated with slower hippocampal atrophy in the absence of amyloidosis, but more rapid neurodegeneration in the presence of amyloid." (PMID 35425899, 2022).
atherosclerosis (1 paper, 2016). A disease characterized by the build-up of fatty material and calcium deposition in the arterial wall resulting in partial or complete occlusion of the arterial lumen. "The dynamic effect of rs7632505 on CHD may be explained by the inhibitory effect of SEMA5B on angiogenesis which is related to aging process (Lähteenvuo and Rosenzweig, 2012) and is purported to be involved in atherosclerosis and other CVDs." (PMID 27790247, 2016).
Burkitt lymphoma (1 paper, 2022). A rare form of malignant mature B-cell non-Hodgkin lymphoma. "Analysing gene expression data of Burkitt lymphoma transcriptome sequencing from African patients revealed six biomarkers (ADAMTSL4, SEMA5B, ADAMTS15, THBS2, SPON1 and THBS1) as possible indicators for diagnostic and prognostic targets towards BL management." (PMID 36354023, 2022).
glioma (1 paper, 2024). A benign or malignant brain and spinal cord tumor that arises from glial cells (astrocytes, oligodendrocytes, ependymal cells). "Expanding our analyses to glioma samples in TCGA, we observed significant negative correlations for SALL2, WNT3, and SEMA5B with METTL7B expression." (PMID 38848215, 2024).
kidney cancer (1 paper, 2024). Primary or metastatic malignant neoplasm involving the kidney. "SDK1 and SEMA5B implicated in prostate and kidney cancer, respectively, represent novel gene candidates with potential implications for understanding osteosarcoma heterogeneity." (PMID 39701601, 2024).
lung carcinoma (1 paper, 2022). "In lung cancer, genomic profiling identified a distinctive molecular signature in asbestos-exposed patients compared to not-exposed, including copy number aberrations in the 2p16, 9q33.1 and 19p13 loci and MRPL1, INPP4A, SDK and SEMA5B somatic mutations." (PMID 35755315, 2022).
neuroblastoma (1 paper, 2020). Neuroblastoma (NB) is the most common solid, extracranial childhood tumor. "While Pea3 upregulates transcription of Sema3D and represses Sema5B, for example, Erm and Er81 upregulate Sema5A and Er81 regulates Unc5C and Sema4G while repressing EFNB3 in SH-SY5Y neuroblastoma cells." (PMID 33097800, 2020).
renal cell carcinoma (1 paper, 2022). "SEMA5B has been demonstrated to contribute to renal cell carcinoma (RCC) progression." (PMID 36354023, 2022).
thromboangiitis obliterans (1 paper, 2022). A rare inflammatory non-necrotizing vascular disease affecting the small- and medium-sized arteries and veins of the upper and lower extremities characterized by endarteritis and vaso-occlusion due to occlusive thrombus development. "Although it is not specific for LEAD, a case-control GWAS of 177 patients with thromboangiitis obliterans (TAO) identified three SNPs (rs376511 in the IL17RC gene, rs7632505 in the SEMA5B gene, and rs10178082 in the RPA3 gene) that were significantly associated with TAO in the Uighur population." (PMID 36142394, 2022).
cancer (7 papers, 2016 to 2025). A tumor composed of atypical neoplastic, often pleomorphic cells that invade other tissues. "Our results showed that SEMA5B was significantly upregulated in RCC cell lines than other cancer types." (PMID 35480320, 2022). "The mRNA expression of SEMA5B was overexpressed in tumors than normal tissues in different types of cancer." (PMID 35480320, 2022). "We also performed the expression levels of SEMA5B in RCC cell lines using the Cancer Cell Line Encyclopedia (CCLE) of the Broad Institute." (PMID 35480320, 2022). "In this study, we conducted a comprehensive differential expression analysis of SEMA5B in normal and tumor from multiomics data integration and analysis in specific cancer." (PMID 35480320, 2022). "Although the effects of SEMA5B were reported more than 30 years ago, the links between SEMA5B and human cancer has remained elusive." (PMID 35480320, 2022). "Additionally, certain SEMAs showed notably high expression in specific cancer types, such as SEMA5B in KIRC." (PMID 40103807, 2025). "Based on the TCGA database, we explored the expression profiles of SEMA5B in pan-cancers by GEPIA2." (PMID 35480320, 2022). "Thus, our study elucidates the clinical value of SEMA5B in KIRC, complements the results of previous studies, and provides a different perspective on how SEMA5B affects cancer progression and metastasis as well as provides insights for improving cancer immunotherapy in the future." (PMID 35480320, 2022).
tumor (6 papers, 2021 to 2025). "This study provides a comprehensive insight into the underlying significance of SEMA5B and would lead to a better understanding of the possible role of SEMA5B in tumor immunology and its clinical value in KIRC." (PMID 35480320, 2022). "Third, this study only focuses on the expression, diagnosis, and prognosis of SEMA5B, the mechanisms by which SEMA5B promotes tumor progression and metastases in KIRC need further elucidation." (PMID 35480320, 2022). "It has been proposed that Mitogen‐Activated Protein Kinases signalling, notch signalling and tumour signalling are the likely pathways regulated by SEMA5B in GC." (PMID 36354023, 2022). "Together, these results demonstrate that SEMA5B could promote the recruitment of immune cells in the tumor microenvironment in KIRC." (PMID 35480320, 2022). "Moreover, the IHC staining results from the HPA database further confirmed the significantly higher protein levels of SEMA5B in tumor tissues." (PMID 35480320, 2022). "Therefore, overexpressed SEMA5B appeared to enhance tumor immunity, synergistically enhance immune cell infiltration of tumor, and further boost the antitumor immune response, and finally inhibit tumor progression." (PMID 35480320, 2022). "Moreover, RT-qPCR confirmed that SEMA5B expression was significantly elevated in ccRCC, and SEMA5B was identified as a target gene of HIF that promoted tumor growth in vivo." (PMID 35480320, 2022). "Control of tumor vascularization was reflected in depletion of mutations in PRDM16, which inhibits angiogenesis by suppressing the expression of a HIF target semaphorin 5B, and in NCO1A, a transcriptional coactivator that upregulates the expression of the VEGFα pro-angiogenic factor." (PMID 34307377, 2021). "Second, we found and confirmed that SEMA5B exhibited a significantly higher mRNA and protein expression profiles in KIRC tumor tissues and cell lines through multiple databases." (PMID 35480320, 2022). "The correlation between SEMA5B and MMRs and DNMT expression and tumor-infiltrating immune cells was explored via TIMER2." (PMID 35480320, 2022). "More importantly, the protein expression of SEMA5B was also elevated in tumor samples when compared to adjacent non-tumor samples (p < 0.001)." (PMID 35480320, 2022). "The relationship between tumor-infiltrating lymphocytes (TIL) and SEMA5B expression was examined." (PMID 35480320, 2022). "In addition, knockdown of NDUFA4L2 in HCC cells has been shown to suppress tumor growth and metastasis, which is consistent with our findings of elevated NDUFA4L2, OLFML2B, SEMA5B, and RASL12 expression in HCC tissues and their significant negative correlation with patient survival." (PMID 41208981, 2025). "Combined with the previous findings, we speculated that the elevated SEMA5B may interfere with SIGLEC15 expression through some unknown mechanism, thus affecting the immune effect of cytotoxic T cells and ultimately prolonging the survival of tumor patients." (PMID 35480320, 2022). "In this study, we found that SEMA5B levels showed a negative correlation with SIGLEC15 in KIRC, suggesting that SEMA5B may effect of SIGLEC15 on tumor immunity." (PMID 35480320, 2022).
neurodegenerative disease (1 paper, 2023). A disorder of the central nervous system characterized by gradual and progressive loss of neural tissue and neurologic function. "Importantly, all of these synaptic regulators (Nos1, Lrp8, Argef2, Sema5b) and other significantly altered splice variants (e.g., Adipor2, Mapk14, Smarca4, Sort1, Mapt) have been linked to AD and other neurodegenerative diseases." (PMID 37819053, 2023).
SEMA5B also shares sentences with these, for which no sentence is quoted: Atrophy (1 paper); breast carcinoma (1); cognitive deficits (1); heart failure (1); Intellectual disability (1); osteosarcoma (1); Stroke (1).